AQP4 (aquaporin 4)
Diseases named in the same sentence as AQP4 in open-access papers (continued):
Sharing a sentence is not in itself a finding about the gene and the disease.
neuromyelitis optica spectrum disorder (continued). "The association of the anti-aquaporin-4 (AQP-4) water channel antibody with neuromyelitis optica (NMO) syndrome has been described from various parts of the world." (PMID 29568625, 2017). "An autoantibody against aquaporin-4 (AQP4 Ab) is highly specific for neuromyelitis optica spectrum disorder and plays a pathogenic role in this disease." (PMID 28199381, 2017). "Autoantibodies against aquaporin-4 (AQP4) cause inflammation in the CNS and can be regarded as pathognomonic for neuromyelitis optica spectrum disorder (NMOSD)." (PMID 28645295, 2017). "Pathogenic autoantibodies associated with neuromyelitis optica (NMO) induce disease by targeting aquaporin-4 (AQP4) water channels enriched on astrocytic endfeet at blood–brain interfaces." (PMID 28184993, 2017). "AQP4 is also the target of pathogenic auto-antibodies in the multiple-sclerosis-like disease Neuromyelitis optica (NMO), causing nerve demyelination and inflammation which leads to paralysis and blindness." (PMID 29077056, 2017). "Neuromyelitis Optica Spectrum Disorders (NMOSD) are associated with autoantibodies (ABs) targeting the astrocytic aquaporin-4 water channels (AQP4-ABs)." (PMID 27571069, 2016). "Damage to astrocytes mediated by aquaporin-4 antibody (AQP4-ab) has been implicated as the cause of neuromyelitis optica spectrum disorder (NMOSD)." (PMID 26920678, 2016). "Astrocytes expressing the aquaporin-4 water channel are a primary target of pathogenic, disease-specific immunoglobulins (IgG) found in patients with neuromyelitis optica (NMO)." (PMID 26423139, 2015). "While ACA is a rare manifestation in some antibody-related disorders, such as in aquaporin-4 (AQP4) antibody-associated neuromyelitis optica (NMO), it is the most frequent or exclusive presentation in others." (PMID 26377319, 2015). "Because severe vision loss was common in this Asian population, we also measured the anti-aquaporin-4 antibody levels and determined mtDNA mutations to exclude neuromyelitis optica and Leber hereditary optic neuropathy, respectively." (PMID 26485719, 2015). "AQP4-IgG obtained from neuromyelitis optica patients causes complement-mediated myelin loss, inflammatory cell infiltration, neuronal and astrocyte death with limited recovery at two weeks." (PMID 24685353, 2014). "It is generally accepted that autoantibodies against aquaporin 4 water channel protein play a pathogenic role in neuromyelitis optica." (PMID 24340077, 2013). "A 40-year-old Japanese woman who was given prednisolone orally after the diagnosis of anti-aquaporin 4 antibody-positive neuromyelitis optica experienced acute, painful loss of vision in her right eye." (PMID 23575376, 2013). "Four patients reacted with 40-kDa optic nerve protein, which corresponded to our control antibodies against aquaporin 4 (AQP4), a water channel protein usually associated with neuromyelitis optica." (PMID 21744285, 2011). "In 70-80% of cases, neuromyelitis optica (NMO) is associated with highly specific serum auto-antibodies to aquaporin-4 (termed AQP4-Ab or NMO-IgG)." (PMID 20825655, 2010). "Data suggest that autoantibodies to aquaporin 4, derived from peripheral B cells, cause the activation of complement, inflammatory demyelination, and necrosis that is seen in neuromyelitis optica." (PMID 19852774, 2009). "Aquaporin-4 antibodies (AQP4-Abs) are a key diagnostic biomarker of neuromyelitis optica spectrum disorder (NMOSD), and anti-Argonaute antibodies (AGO-Abs) have recently been reported in a range of autoimmune neurological conditions, although their clinical significance remains undetermined." (PMID 42039156, 2026). "The use of FCBA‐IF may result in underrecognition of both MOG antibody‐associated disease (MOGAD) and AQP4‐IgG seropositive neuromyelitis optica spectrum disorder (NMOSD)." (PMID 39901660, 2025).
neuromyelitis optica spectrum disorder (continued). "AQP4-IgG positive NMOSD, previously known as Devic’s disease, is an autoimmune disorder characterized by inflammation and demyelination of the optic nerves and spinal cord, often associated with antibodies against aquaporin-4 (AQP4)." (PMID 40611612, 2025). "This study aimed to evaluate the potential utility of glial fibrillary acidic protein (GFAP) and neurofilament light chain (NfL) as biomarkers of disease activity in AQP4-IgG-positive neuromyelitis optica spectrum disorder (NMOSD) and MOG antibody-associated disease (MOGAD)." (PMID 41155859, 2025). "Notably, the aquaporin-4 immunoglobulin G (AQP4-IgG) seropositive subtype (historically termed neuromyelitis optica) is associated with a significantly worse prognosis." (PMID 41261715, 2025). "Background and aims: The impact of pain, fatigue, depression, spasticity and bladder dysfunction in patients with myelin oligodendrocyte glycoprotein antibody‐associated disease (MOGAD) and aquaporin‐4‐IgG‐seropositive neuromyelitis optica spectrum disorder (NMOSD‐AQP4+) is still unclear." (PMID 40542581, 2025). "Determining if AQP4 regulates transport of solutes from the CSF to optic nerve is of particular importance in AQP4-IgG seropositive neuromyelitis optica spectrum disorder (NMOSD) where autoantibodies to AQP4 cause loss of AQP4 from optic nerve astrocytes and optic neuritis." (PMID 38178155, 2024). "The effect of smoking on the resolution of magnetic resonance imaging (MRI) lesions in patients with neuromyelitis optica spectrum disorders with aquaporin-4 positive antibody (NMOSD-AQP4) and myelin oligodendrocyte glycoprotein antibody-associated disease (MOGAD) has not been studied before." (PMID 37528605, 2023). "The AQP4 intronic rs3763040 polymorphism has also been related to neuromyelitis optica and to the progression of Alzheimer’s disease, meaning that it is an SNP with functional consequences or in linkage disequilibrium with another polymorphism that has functional consequences." (PMID 37724184, 2023). "Besides MS, retinal vessel loss also occurs during anti-aquaporin 4 antibody positive neuromyelitis optica spectrum disorders." (PMID 38090586, 2023). "Neuromyelitis optica spectrum disorders (NMOSD) are severe inflammatory diseases of the central nervous system (CNS) most frequently associated with the presence of pathogenic serum autoantibodies against the water channel aquaporin 4 (AQP4)." (PMID 36811295, 2023). "In the CNS, the best-known example of AQP antibodies (AQP-Abs) are the antibodies against AQP4, which are associated with the majority of neuromyelitis optica spectrum disorder (NMOSD) cases, an inflammatory, antibody-mediated astrocytopathy resulting in secondary demyelination of the CNS." (PMID 37629163, 2023). "Moreover when AQP-4 was knocked-out there was BRB impairment and in a model of neuromyelitis optica, AQP-4 loss led to increased retinal thickness." (PMID 36347836, 2022). "We could recently show that retinal vessel loss occurs subclinically in patients with neuromyelitis optica spectrum disorders and antibodies against aquaporin-4." (PMID 36439131, 2022). "In addition, a concomitant involvement of the peripheral nervous system (PNS) has been described either in association with AQP4 antibodies-positive neuromyelitis optica spectrum disorder (NMOSD), or MOG-associated disease." (PMID 36498887, 2022). "Neuromyelitis optica spectrum disorder is an autoimmune astrocytopathy of the CNS with secondary demyelination, which can be associated with a specific auto-antibody against the antigen aquaporin-4 (AQP4) in 50–90% of cases." (PMID 34867701, 2021). "High sNfL levels were also found in patients with neuromyelitis optica spectrum disorders (NMOSDs) associated with aquaporin-4 (AQP-4) antibodies and in patients with the anti-MOG-Ab-associated disorder (MOGAD) indicating the presence of axonal damage in all these disorders." (PMID 34867740, 2021).
neuromyelitis optica spectrum disorder (continued). "As anti-AQP4 antibodies are found to be associated with not only lesions in the optic nerves and spinal cord, but also those in other sites of the central nervous system, the concept of neuromyelitis optica spectrum disorder (NMOSD) has been proposed." (PMID 33917929, 2021). "Background and purpose: Immunoadsorption (IA) is an antibody-depleting therapy used to treat neuromyelitis optica spectrum disorder (NMOSD) associated to antiaquaporin 4 (anti-AQP4-IgG) and antimyelin oligodendrocyte glycoprotein (anti-MOG-IgG) serum autoantibodies." (PMID 33763015, 2021). "Although LETM is classically related to AQP4-antibodies (Ab) neuromyelitis optica spectrum disorders (NMOSD) or more recently to MOG-Ab associated disease, alternative diagnoses have to be excluded such as vascular, granulomatosis, paraneoplastic, metabolic, and infectious diseases." (PMID 32326965, 2020). "The presence of anti-SSA/Ro antibodies may be associated with anti-aquaporin-4 antibody positivity in neuromyelitis optica spectrum disorder." (PMID 33374330, 2020). "The mechanism underlying the pathology of neuromyelitis optica spectrum disorders (NMOSD) remains unclear even though antibodies to the water channel protein aquaporin-4 (AQP4) on astrocytes play important roles." (PMID 32983166, 2020). "Neuromyelitis optica spectrum disorder (herein called NMO) is an inflammatory demyelinating disease that can be initiated by binding of immunoglobulin G autoantibodies (AQP4-IgG) to aquaporin-4 on astrocytes, causing complement-dependent cytotoxicity (CDC) and downstream inflammation." (PMID 30851734, 2019). "Additionally, mechanistic studies assessing the role of Müller cells should be performed in the context of both MS, but also neuromyelitis optica spectrum disorder, where AQP4-mediated Müller pathology has been implicated." (PMID 31315675, 2019). "Neuromyelitis optica spectrum disorders are severe autoimmune inflammatory diseases of the central nervous system associated with the presence of immunoglobulin G antibodies against the water channel protein aquaporin-4." (PMID 30696485, 2019). "Microparticles of aquaporin-4 represent subcellular arrangements that may influence the pathogenesis of neuromyelitis optica spectrum disorders and may serve as biomarkers for the underlying cellular disturbances." (PMID 30696485, 2019). "Loss of function in AQPs may cause congenital cataracts (AQP0), diabetes insipidus (AQP2), and autoantibodies against AQP4 cause the autoimmune demyelinating disease neuromyelitis optica." (PMID 30555637, 2018). "Aquaporin-4 antibodies are pathogenic in neuromyelitis optica spectrum disorders (NMOSD)." (PMID 29447335, 2018). "Autoantibodies against AQP4 cause the autoimmune demyelinating disease neuromyelitis optica." (PMID 30555637, 2018). "AQPs, particularly AQP4, are not only implicated in cancer, they also play a role in the development and progression of demyelinating diseases such as neuromyelitis optica, and metabolic pathologies such as obesity, dermatological pathologies, edema, and glaucoma." (PMID 30555637, 2018). "Autoantibodies in demyelinating and other inflammatory neurological diseases are of scientific and clinical interest, and are often associated with pathogenetic events, such as aquaporin-4 (AQP4) autoantibodies in neuromyelitis optica spectrum disorders (NMOSD)." (PMID 28327523, 2017). "Neuromyelitis optica immunoglobulin G might target cellular processes of Müller cells and cause their loss of AQP4 reactivity, when AQP4‐specific T cells open the blood–retina barrier in the outer plexiform layer." (PMID 28344667, 2017). "In fact, most neurological autoantibodies of proven pathogenic impact, such as antibodies to AQP4 in neuromyelitis optica, acetylcholine receptor in myasthenia gravis, VGCC in Lambert-Eaton syndrome and mGluR1 in paraneoplastic cerebellar degeneration, target cell-surface-expressed proteins." (PMID 27776522, 2016).
neuromyelitis optica spectrum disorder (continued). "Neuromyelitis optica (NMO) is a severe demyelinating disorder of the central nervous system (CNS) associated with the presence of an autoimmune antibody response (AQP4-IgG) against the water channel aquaporin-4 (AQP4)." (PMID 25626447, 2015). "One area of recent progress is the immunosuppressive approach to block the onset of neuromyelitis optica by a combination of methods based on anti-AQP4 antibody binding to pathogenic autoantibodies and screening of blockers of the autoantibody-AQP4 interaction." (PMID 25904843, 2015). "However, it is beyond doubt that aquaporin-4 antibodies are highly pathogenic in neuromyelitis optica since they were studied extensively." (PMID 24817862, 2014). "Antibodies against AQP4 are associated with the clinical spectrum of neuromyelitis optica." (PMID 23035757, 2012). "Most neurological autoantibodies of proven pathogenic impact, such as antibodies to AQP4 in neuromyelitis optica, acetylcholine receptor in myasthenia gravis, VGCC in Lambert Eaton syndrome, and mGluR1 in paraneoplastic cerebellar degeneration in fact target transmembrane proteins." (PMID 20226058, 2010). "Beside MS, ADS in children under 18 years of age may also include anti-aquaporin-4-associated neuromyelitis optica spectrum disorder (AQP4-NMOSD), myelin oligodendrocyte glycoprotein antibody-associated disorder (MOGAD), or acute disseminated encephalomyelitis (ADEM) with encephalopathy." (PMID 39845956, 2024). "Indeed, complement activation is recognized as a major pathogenic or contributing factor in neuromyelitis optica spectrum disorders (NMOSDs) and myasthenia gravis (MG), where AABs form stable surface complexes on aquaporin-4 (AQP4) or acetylcholine receptors (AChRs), respectively." (PMID 36613687, 2022). "We report the case of a 25-year-old pregnant woman who was diagnosed with aquaporin-4 antibody-positive (AQP4+) neuromyelitis optica spectrum disorder (NMOSD) at 19 weeks of gestation." (PMID 42253981, 2026). "Aquaporin-4 antibody-positive neuromyelitis optica spectrum disorder (AQP4+ NMOSD) is an inflammatory disease of the central nervous system." (PMID 41596603, 2026). "The disease course of AQP4-antibody seropositive neuromyelitis optica spectrum disorder (AQP4-Ab + NMOSD) is unpredictable and variable." (PMID 41528504, 2026). "AQP4-Ab-positive ON is classified as neuromyelitis optica spectrum disorder (NMOSD), a condition distinct from multiple sclerosis (MS), whereas MOG-Ab-positive ON is classified as MOG-IgG associated disorder (MOGAD)." (PMID 40377800, 2025). "For instance, a recent study on neuromyelitis optica spectrum disorder (NMOSD) successfully characterized aquaporin 4 (AQP4)‐reactive T cells and found evidence of oligoclonal T cell responses associated with an exhaustion gene signature." (PMID 40534591, 2025). "Serum glial fibrillary acidic protein (sGFAP) is associated with disease activity in aquaporin-4-immunoglobulin G-seropositive neuromyelitis optica spectrum disorders (AQP4-IgG+NMOSD)." (PMID 40693183, 2025). "Most patients with aquaporin‐4 antibody‐positive neuromyelitis optica spectrum disorder (AQP4‐IgG NMOSD) require life‐long immunosuppression to prevent relapses." (PMID 40087846, 2025). "Neuromyelitis optica spectrum disorder is typically diagnosed by the detection of AQP4 antibodies, while MS is characterized by oligoclonal bands and plaques on MRI." (PMID 40687165, 2025). "Advances in complement-targeted therapeutics have been particularly striking in diseases such as myasthenia gravis (MG) and aquaporin-4 IgG-positive neuromyelitis optica spectrum disorder (AQP4 + NMOSD)." (PMID 41409222, 2025). "This case illustrates an atypical presentation of neuromyelitis optica spectrum disorder, with peripheral neurogenic syndrome and syringomyelia in a 52-year-old patient confirmed by the presence of AQP4 antibodies." (PMID 40687165, 2025).
neuromyelitis optica spectrum disorder (continued). "As proof-of-concept, we investigated the spatial association between brain damage and gene expression in aquaporin-4-IgG-positive neuromyelitis optica spectrum disorder (AQP4 + NMOSD)." (PMID 39891565, 2025). "Aquaporin‐4‐IgG‐positive neuromyelitis optica spectrum disorder (AQP4‐IgG+ NMOSD) is an autoimmune disease of the central nervous system that primarily manifests with optic neuritis and longitudinally extensive transverse myelitis." (PMID 40492480, 2025). "A more extreme example of CNS inflammation with high serum IFN levels is neuromyelitis optica (NMO), where antibodies to the aquaporin-4 water channels of astrocyte foot processes cause severe inflammation, neuron destruction, and secondary demyelination." (PMID 40971988, 2025). "The aquaporin‐4 immunoglobulin G (AQP4‐IgG) antibody positive neuromyelitis optica spectrum disorder (NMOSD) is a non‐fatal but highly disabling disorder, making it harmful for patients." (PMID 40810769, 2025). "Aquaporin-4 neuromyelitis optica spectrum disorder (AQP4-NMOSD) often coexists with other autoimmune diseases (AIDs), whereas such comorbidities are less common in myelin oligodendrocyte glycoprotein antibody disease (MOGAD)." (PMID 40495001, 2025). "Neuromyelitis optica is an autoimmune disease affecting the central nervous system driven primarily by autoantibodies against the water channel protein AQP4." (PMID 40625741, 2025). "Another distinguishing marker is the presence of neuromyelitis optica immunoglobulin (NMO-IgG), which binds to AQP4 channels and indicates high-risk syndromes." (PMID 40486405, 2025). "Although it shares overlapping features with multiple sclerosis (MS) and aquaporin-4-positive neuromyelitis optica spectrum disorder (AQP4-NMOSD), MOGAD represents a distinct pathological and clinical entity." (PMID 41583138, 2025). "Totally 1,774 subjects were initially enrolled, including 1,082 HCs, 290 AQP4 antibody positive neuromyelitis optica spectrum disorders (AQP4 + NMOSD) and 402 multiple sclerosis (MS) cases." (PMID 40898200, 2025). "Neuromyelitis optica spectrum disorder (NMOSD) is an autoimmune disease characterized by inflammation of the optic nerves and spinal cord, often associated with anti-aquaporin-4 antibodies." (PMID 40551924, 2025). "The most common cause of brainstem-localized hyperemesis is its incidence as secondary to a neuromyelitis optica spectrum disorder (NMOSD), an autoimmune demyelinating disorder caused by autoantibodies to Aquaporin 4 (AQP4)." (PMID 40724523, 2025). "Post-discharge, a cell-based assay confirmed the diagnosis of neuromyelitis optica spectrum disorder (NMOSD) by detecting positive anti-AQP4-Ab." (PMID 41226015, 2025). "The coexistence of spinal cord lesions and GFAP/AQP4 antibody seropositivity in this case necessitated critical differentiation from primary autoimmune astrocytopathies and neuromyelitis optica spectrum disorders (NMOSD)." (PMID 40688088, 2025). "For example, a mouse model of neuromyelitis optica (NMO) was developed through intradermal immunization with human AQP4 peptide 201–220, which induced paralysis in C57BL mice, similar to human NMO." (PMID 40282759, 2025). "Neuromyelitis optica spectrum disorder (NMOSD) is a severe autoimmune condition of the central nervous system (CNS), often associated with aquaporin‐4 antibodies (AQP4‐IgG)." (PMID 40492601, 2025). "Neuromyelitis optica spectrum disorder (NMOSD) involves aquaporin-4-mediated astrocyte injury, potentially impairing the glymphatic system." (PMID 41459546, 2025). "There were overlapping clinical features; however, crucial radiological and pathological differences distinguished MOGAD from multiple sclerosis (MS) and aquaporin-4-IgG seropositive neuromyelitis optica spectrum disorder (AQP4-IgG NMOSD)." (PMID 40740785, 2025).